WRN (WRN RecQ like helicase)
Diseases named in the same sentence as WRN in open-access papers (continued):
Sharing a sentence is not in itself a finding about the gene and the disease.
esophageal cancer (2 papers, 2021 to 2022). A primary or metastatic malignant neoplasm involving the esophagus. "A case-control study looking at single-nucleotide polymorphisms in WRN identified WRN c.4330T > C to be associated with increased susceptibility to esophageal carcinoma." (PMID 35782872, 2022).
glioma (2 papers, 2010 to 2022). A benign or malignant brain and spinal cord tumor that arises from glial cells (astrocytes, oligodendrocytes, ependymal cells). "Correlation analysis of 173 glioma patient samples (r = 0.52, p < 0.001) showed that FEN1 was positively correlated with WRN expression." (PMID 35414100, 2022). "Moreover, as FEN1 regulates the expression and function of many molecules, there may be additional effects of FEN1 inhibition that contribute to sensitization of glioma cells to DNA-PKcs dysfunction, either cooperating with BRCA1/2, RAD51 or WRN." (PMID 35414100, 2022).
Hereditary breast cancer (2 papers, 2021 to 2023). Breast carcinoma that has developed in relatives of patients with history of breast carcinoma. "Multiple studies have reported an association between WRN variants and hereditary breast cancer as well as HBOC." (PMID 37461096, 2023). "The identified variant was interpreted as pathogenic according to the ACMG guidelines, thereby introducing WRN as a potential candidate gene for hereditary breast cancer." (PMID 34164337, 2021).
hereditary cancer syndrome (2 papers, 2021 to 2023). "WRN deficient function may contribute to CRC development that is valuable for further investigation as a candidate gene in hereditary cancer syndrome diagnosis." (PMID 34164337, 2021).
mesenchymal neoplasms (2 papers, 2012 to 2013). "Since patients with WRN gene germ line mutations develop a wide variety of epithelial and mesenchymal tumors, a tumor suppressor function for WRN is anticipated and it is supported by the very frequent loss of heterozygosity at the chromosomal WRN region, 8p11.2–p12 in different cancers." (PMID 22778947, 2012).
neuroblastoma (2 papers, 2020 to 2023). Neuroblastoma (NB) is the most common solid, extracranial childhood tumor. "We also detected rare genetic germline variants in DNA repair genes (e.g., BARD1, BRCA2, CHEK2, and WRN) that might cooperate with somatically acquired variants in these patients with highly aggressive recurrent neuroblastoma." (PMID 33384420, 2020).
papillary carcinoma (2 papers, 2019 to 2021). A malignant epithelial neoplasm characterized by a papillary growth pattern. "Furthermore, the association of the follicular and papillary carcinomas with the WRN c.3139-1G>C (exon 26 skip) and c.1105C>T (p.R369*) variants was found in WS patients, respectively." (PMID 34164337, 2021).
rapadilino syndrome (2 papers, 2012 to 2020). "While some mutations in RECQL4 also lead to loss of protein, both missense mutations and the deletion of exon 7 common in RAPADILINO syndrome stand in contrast to the truncations of WRN and BLM." (PMID 23238538, 2012).
B-cell neoplasm (1 paper, 2021). A group of heterogeneous lymphoid tumors generally expressing one or more B-cell antigens or representing malignant transformations of B-lymphocytes. "Out of 15 patients, 4 (26.6%) with subsequent mature B-cell neoplasms had germline pathogenic mutations in cancer susceptibility genes; MUTYH and WRN in 2 subsequent DLBCL patients and RAD50 and LZTR1 in 2 subsequent PCM patients." (PMID 34093829, 2021).
Brain atrophy (1 paper, 2019). Partial or complete wasting (loss) of brain tissue that was once present. "However, recent studies suggest that brain atrophy occurs in WS patients, and a linkage between WRN polymorphisms and several brain disorders has been reported." (PMID 31754102, 2019).
brain tumor (1 paper, 2023). "The other missenses mutations in TYRP1 (c.C785T, p.T262M) and WRN (c.G1149T: p.L383F, and c.G2983A: p.A995T) were present in a heterozygous state in the patient and his brother with a brain tumor, while it was absent in the unaffected brother." (PMID 38028607, 2023).
breast tumors (1 paper, 2016). "Low WRN mRNA expression was significantly associated with molecular phenotypes: PAM50.Her2, PAM50.LumB, Genufu subtype (ER+/Her2-/High proliferation) and Genufu subtype (Her2 positive) breast tumors (ps≤0.01)." (PMID 26959889, 2016). "In a small cohort of breast tumors (n = 58), 17.2% (10/58) showed WRN inactivation although the authors did not describe any clinicopathological associations in that study." (PMID 26959889, 2016).
cervical disease (1 paper, 2020). "To investigate this, we utilized cervical liquid-based cytology samples from a cohort of HPV16+ patients representing the progression of cervical disease (CIN1 to CIN3) and compared this to HPV- normal cervical tissue for SIRT1/WRN protein and mRNA expression." (PMID 32938703, 2020). "Together, these data support our previous studies demonstrating that SIRT1 modulates WRN expression in a posttranslational manner (i.e., by deacetylation) and suggest that the SIRT1-WRN axis may contribute to cervical disease progression." (PMID 32938703, 2020).
Cognitive impairment (1 paper, 2025). Abnormal cognition is characterized by deficits in thinking, reasoning, or remembering. "WRN‐deficient animal models exhibit neurodegenerative features such as cognitive impairment, behavioral deficits, neuroinflammation, and mitochondrial dysfunction, mimicking aspects of aging‐related neural decline." (PMID 40530580, 2025).
colonic adenocarcinoma (1 paper, 2025). "A pathogenic variant, c.1105C>T (p.Arg369), that was identified in WRN led to the genetic instability associated with her mutated WRN protein likely contributing to the development of multiple malignancies including urothelial carcinoma, BCC, TNBC, colonic adenocarcinoma, and pancreatic IPMN." (PMID 39958080, 2025).
colorectal adenocarcinoma (1 paper, 2022). The most common type of colorectal carcinoma. "Besides, we have also analyzed patient survival from TCGA database of colorectal adenocarcinoma (available at c‐Bioportal) and found WRN‐deficient cancer patient has more survival rate in contrast to increased WRN expressing cancer patients." (PMID 35582959, 2022).
gastric tumor (1 paper, 2013). "Based on previous studies,to analyze the methylation status of the promoter-associated CpG island of both WRN and SULF2, we collected 102 samples of primary gastric tumors." (PMID 24359226, 2013).
gynecologic cancer (1 paper, 2012). "This is the first report to show a relationship between the methylation of the WRN gene and sensitivity to CPT-11 in gynecologic cancer." (PMID 22797812, 2012). "This is the first report to show a relationship between the methylation of the WRN gene and sensitivity to CPT-11 in gynecological cancers." (PMID 22797812, 2012).
head and neck squamous cell carcinoma (1 paper, 2015). A squamous cell carcinoma that arises from any of the following anatomic sites: lip and oral cavity, nasal cavity, paranasal sinuses, pharynx, larynx, and salivary glands. "WRN was considered as a cancer therapeutic target in hypopharyngeal carcinomas, which have the worst prognosis among head and neck squamous cell carcinomas (HNSCC) with a rapidly rising incidence." (PMID 25991664, 2015).
jejunal cancer (1 paper, 2014). A malignant neoplasm involving the jejunum. "From our exome-capture sequencing results, mutations of WRN may be important as they represent the only genetic defect in this jejunal cancer." (PMID 25018888, 2014). "Of the mutations found in the gene sequencing tests, only WRN may relate to jejunal cancer." (PMID 25018888, 2014). "Our genetic tests on genes such as WRN lead us to recognize possible pathologies to jejunal cancer." (PMID 25018888, 2014).
liposarcoma (1 paper, 2023). A usually painless malignant tumor that arises from adipose tissue. "Reportedly, a patient with a heterozygous mutation in the WRN gene and a retroperitoneal liposarcoma had dramatic renal and hematological toxicity after cytotoxic chemotherapy." (PMID 37130431, 2023).
lung adenocarcinoma (1 paper, 2010). A carcinoma that arises from the lung and is characterized by the presence of malignant glandular epithelial cells. "Multiple genetic pathways defined by gains of MYC, deletions of RB1 and WRN or gains on 7p and 7q are involved in lung adenocarcinoma in never smokers." (PMID 21151896, 2010).
microcephaly (1 paper, 2024). A congenital or acquired developmental disorder in which the circumference of the head is smaller than normal for the person's age and sex. "Patient 29 had a disease-causing variant in WRN, which explains the multiple features of accelerated aging in addition to microcephaly and mental retardation." (PMID 37940764, 2024).
Obesity (1 paper, 2008). Accumulation of substantial excess body fat. "WRN polymorphisms may also have relevant clinical significance for "normal states" such as stress, obesity, aging or acute inflammation, because they are characterized by high levels of insulin, TNFα, TGFβ." (PMID 18312663, 2008).
ovarian serous cystadenocarcinoma (1 paper, 2017). A malignant serous cystic epithelial neoplasm arising from the ovary. "In addition, the executive step in BER process that is controlled by WRN and its co-factor PNK kinase is most probably inactive, because both WRN and PNK kinase are deregulated at the expression level and mutated in Ovarian Serous Cystadenocarcinoma, but not in Adenocortical Carcinoma." (PMID 28415074, 2017).
Simpson-Golabi-Behmel syndrome (1 paper, 2020). Simpson-Golabi-Behmel syndrome is a rare X-linked multiple congenital anomalies syndrome, characterized by pre- and postnatal overgrowth, distinctive craniofacial features, variable congenital malformations, organomegaly and an increased tumor risk. "In addition to the WRN−/− and BLM−/− ESC lines generated using CRISPR/Cas9, we also attempted shRNA-mediated WRN or BLM knockdown in primary adipose-derived stem cells and the Simpson-Golabi-Behmel Syndrome (SGBS) human preadipocyte line." (PMID 32367056, 2020).
Skin ulcer (1 paper, 2021). A discontinuity of the skin exhibiting complete loss of the epidermis and often portions of the dermis and even subcutaneous fat. "Thus, cytoplasmic accumulation of WRN protein can be an indicator of the decreasing drainage function of the lymphatic vessels and the increased risk of skin ulcers and calcification in the lymphatic vessels." (PMID 34958633, 2021).
small bowel cancer (1 paper, 2014). "Little information exists in the literature relating small bowel cancer and the WRN gene." (PMID 25018888, 2014).
systemic sclerosis (1 paper, 2021). A chronic disorder, possibly autoimmune, marked by excessive production of collagen which results in hardening and thickening of body tissues. "Interestingly, autoantibodies against WRN (Werner helicase) and a lower expression rate of WRN were observed in systemic sclerosis, suggesting a possible pathogenic link of sclerotic skin changes." (PMID 34381458, 2021).
T-cell lymphoma (1 paper, 2014). "Our result showed that the WRN 787 TT genotype was associated with a decreased risk of only NHL, and NHL including DLBCL and T-cell lymphoma for BRCA1 871 TT genotype." (PMID 24756092, 2014).
telangiectasia and (1 paper, 2019). "Activation of the DDR stimulates WRN activity, and subsequently, levels decrease over a 12-h period following ATR (ataxia telangiectasia and Rad3 related) phosphorylation; WRN is turned over via the proteasome." (PMID 30890607, 2019).
teratoma (1 paper, 2020). A non-seminomatous germ cell tumor characterized by the presence of various tissues which correspond to the different germinal layers (endoderm, mesoderm, and ectoderm).
testis cancer (1 paper, 2024). "Almost all of the top-performing genes were that of over-expression, with PMS2 in THYM; CARD11, LASP1, STIL, POLE, KMT2C, and CLIP1 in testis cancer; ERC1, WRN, OLIG2, FANCC, and ACSL6 in ACC; and SOX2 and NDRG1 in ESCA leading in performance with AUCs ranging 0.832-0.911." (PMID 38491101, 2024).
cancer (187 papers, 2005 to 2026). A tumor composed of atypical neoplastic, often pleomorphic cells that invade other tissues. "Most notably, we used the KMT2DLOF mutational status to identify MSI cancer cell lines sensitive to WRN inhibitors, which are in phase I clinical trials." (PMID 39578878, 2024). "Shortly after these Pan-Cancer Atlas results were published, several groups identified a synthetic lethal interaction between WRN loss and mismatch repair deficiency in human epithelial cancers [reviewed in Chan 2022 monograph]." (PMID 38994931, 2024). "It should be feasible to find that subset of microsatellite unstable cancers with numerous TA dinucleotide expansions that would be susceptible to killing by a WRN-specific inhibitor." (PMID 39125869, 2024). "More recently, CRISPR screening in large panels of cancer cell lines revealed WRN—encoding Werner syndrome helicase—as a selective essential gene in microsatellite unstable cancers." (PMID 38638566, 2024). "For instance, Werner syndrome caused by mutations of WRN is characterized by features of premature aging and a significantly increased incidence of cancer." (PMID 36583333, 2023). "The development possibility of novel therapeutic agents that target WRN for MSI-associated cancers by pharmacological inhibition of WRN helicase function has been reported." (PMID 37130431, 2023). "Another complementary study of CRISPR-Cas9 screens in 324 cancer cell lines also linked MSI-associated cancers to WRN." (PMID 35267530, 2022). "Loss of heterozygosity involving the WRN loci at chromosome 8p11.2-p12 occurs frequently in many different cancers, pointing to its role as a tumor suppressor gene." (PMID 35782872, 2022). "We demonstrate that WRN helicase inhibition results in preferential cell killing of multiple BRCA2-deficient cancer cell lines with distinct tissue origins, suggesting an avenue of exploration for therapy." (PMID 34772932, 2021). "Given the widely known association between cancer and WS, WRN is a specific target to develop a therapy for microsatellite instability-high (MSI-H) cancer cells." (PMID 34943966, 2021). "WRN mutations were found more frequently in right-sided than in left-sided cancers (5.4% vs. 0.7%, p < 0.0001)." (PMID 32455893, 2020). "Mutations in human RecQ helicases BLM, WRN and RecQL4 cause incurable disorders characterized by genome instability, increased cancer predisposition and premature adult-onset aging." (PMID 32085395, 2020). "The correlation of chromosome aberrations and nuclear abnormalities with MSI-H status following loss of WRN function indicate that genome integrity defects are responsible for the profound reduction in viability of MSI-H cancer cells." (PMID 30910006, 2019). "Because WRN deficiency is associated with cancer susceptibility, this study provides further evidence that replication-transcription collisions contribute to develop human disease and cancer." (PMID 30657978, 2019). "ATP-binding deficient variants of WRN fail to rescue the viability phenotype of WRN-depleted MSI-H cancer cells." (PMID 30910006, 2019). "Interesting but uncertain—according to specific population findings—clinical prediction related to WRN dysregulation in some diseases such as cancer, remains to be clarified with WRNp variants different from the truncating or non‐functional." (PMID 30584990, 2018). "In particular, WRN has been reported to be frequently deleted in CC, and its deficiency apparently predisposes to various types of cancer." (PMID 29755661, 2018). "WRN promotes DNA repair and genome stability, and consequently patients with WS are predisposed to various cancers." (PMID 29043077, 2017). "Several other studies have indicated an association between the Arg1367 allele of the WRN gene product and different cancer types." (PMID 27863399, 2016). "The exact cellular impact of these polymorphisms in the WRN gene and how they contribute to chemical toxicity and cancer predisposition remains rudimentary." (PMID 27863399, 2016).